ANXA1 (annexin A1)
Diseases named in the same sentence as ANXA1 in open-access papers (continued):
Sharing a sentence is not in itself a finding about the gene and the disease.
breast carcinoma (continued). "This study underscores the potential role of ANXA1 and its association with MHC‐II in mediating resistance to PD‐1/PD‐L1 blockade in breast cancer." (PMID 40744683, 2025). "Treatment with APS results in a significant decrease in EGFR levels and a marked increase in ANXA1 levels in breast cancer cells." (PMID 38794206, 2024). "This study has several limitations, as it included a small number of participants, even though the current data suggest the potential of ECM1 and ANXA1 in the uEVs to distinguish breast cancer patients." (PMID 39040439, 2024). "The expression levels of ECM1 and ANXA1 were also confirmed in the uEVs of MMTV-PyMT transgenic breast cancer mouse models." (PMID 39040439, 2024). "Another study involved stimulating MCF-7 breast cancer cells with various estrogen levels and exposure of physiologic estrogen levels led to upregulation of ANXA1." (PMID 38892394, 2024). "The findings indicated a significant decrease in the levels of ECM1 and ANXA1 in the uEVs of breast cancer patients after surgery, compared to before surgery." (PMID 39040439, 2024). "A detailed study with a larger cohort is necessary to establish ECM1 and ANXA1 in the uEVs as potential biomarkers for breast cancer before starting clinical application." (PMID 39040439, 2024). "ANXA1 overexpression in tumor cell cytoplasm has been reported in various cancers, including breast cancer and squamous cell carcinoma." (PMID 38893148, 2024). "To explore the impact of annexins in breast cancer, we compared the expression of ANXA1, ANXA2 and ANXA4 in MDA-MB-231 and MCF7 cells at the protein and mRNA level." (PMID 38092984, 2023). "Low expression of ANXA1 has been confirmed in breast cancer tumor tissues, but there is still overexpressing ANXA1 in poorly differentiated, invasive tumors, therefore, it is crucial to further clarify the roles and mechanisms between ANXA1 and malignancies." (PMID 36678567, 2023). "Estrogen receptor signaling can directly or indirectly modulate ANXA1 levels in breast cancer cells." (PMID 37507468, 2023). "Understanding these regulatory mechanisms holds promise for the development of targeted therapies aimed at modulating ANXA1 expression and improving breast cancer treatment outcomes." (PMID 37507468, 2023). "As well, NTF4 suppresses the proliferation of breast cancer cells by increasing the phosphoserine and sumoylation level of ANXA1 and the interaction of ANXA1 with importin β." (PMID 36632451, 2023). "The precise mechanisms and triggers of ANXA1 expression in breast cancer are still being investigated." (PMID 37507468, 2023). "We here confirmed that B16F10 cells constitutively express FPR1 and FPR2, and data from the literature show that AnxA1 binds to both receptors and leads to cancer progression, such as breast cancer." (PMID 36766767, 2023). "ANXA1, a calcium-dependent phospholipid-binding protein, playing a significant role in the progress of tumors in various tumor types, including breast cancer, colorectal cancer, and PC." (PMID 37941546, 2023). "Inflammatory cytokines, such as IL-6 and TNF-α, have been found to upregulate ANXA1 expression in breast cancer cells." (PMID 37507468, 2023). "Conversely, in the mouse mammary tumour cell line 168FARN, the knockdown of ANXA1 inhibited the invasion and metastasis of breast cancer, with less expression of epithelial–mesenchymal transition (EMT) markers, wave proteins and myosin light-chain kinase." (PMID 36936694, 2023). "ANXA1 has been documented to be differentially expressed during the progression of breast cancer toward a more malignant state." (PMID 35382852, 2022). "ANXA1 is a calcium-dependent phospholipid-binding protein considered to play an important role in tumorigenesis in multiple types of cancer, including breast cancer, colorectal cancer, and more." (PMID 35428170, 2022).
breast carcinoma (continued). "In contrast, another study suggested that ANXA1 downregulated in progressed human breast cancer and acted as a suppressor of both epithelial‐mesenchymal transition and metastasis in murine and human cells and tumours." (PMID 35770335, 2022). "Upregulation of AnxA1 was observed in breast cancer, hepatocellular carcinoma and melanoma, whereas downregulation was observed in gastric, prostate and oral cancer." (PMID 36123610, 2022). "So, the level of ANXA1 can also predict the sensitivity to trastuzumab in targeted therapy for breast cancer." (PMID 36276152, 2022). "Previous studies have reported that, even in the same breast cancer, the expression and role of ANXA1 vary in different subtypes." (PMID 35770335, 2022). "Annexin A1 (AnxA1) is a pleiotropic protein that exerts essential roles in breast cancer (BC) growth and aggressiveness." (PMID 35626741, 2022). "Previous studies have shown that high ANXA1 expression is bound up with a bad prognosis in patients with colorectal cancer and breast cancer." (PMID 36741702, 2022). "ANXA1 has been increasingly described to be highly expressed in metastatic basal-like breast cancer (BLBC) and triple-negative breast cancer (TNBC)." (PMID 35382852, 2022). "Expression of ANXA1 is significantly higher in basal and normal-like breast cancer compared to luminal breast cancer (P < 0.01)." (PMID 35382852, 2022). "The requirement of ANXA1 in these functions was examined using a Crispr/Cas9 deletion mutant of ANXA1 in 4T1 breast cancer cells as well as BV2 microglia." (PMID 35382852, 2022). "The papers retrieved were based on two different sets of key words such as “Annexin A1” or “Lipocortin 1” and “Breast cancer” or “TNBC”." (PMID 35897832, 2022). "In particular, Annexin-A1 (ANXA1) is a glucocorticoid regulated gene which plays an essential role in breast cancer development both in vitro and in vivo." (PMID 35664067, 2022). "The present study uncovered a network encompassing autocrine/paracrine ANXA1 signaling between metastatic mammary cancer cells and microglia that drives microglial recruitment and activation." (PMID 35382852, 2022). "Metastatic 4T1 mammary cancer cells secrete ANXA1 to promote microglial migration, which in turn, enhances tumor cell migration." (PMID 35382852, 2022). "Intriguingly, genetic ablation of ANXA1 in 4T1 metastatic mammary cancer cells only modestly affect the pro- and anti-inflammatory gene expression profiles of BV-2 microglia stimulated by 4T1 CM." (PMID 35382852, 2022). "Our comprehensive analysis of TNBC cell lines with Annexin A1 knockdown demonstrates a novel cell-autonomous role for Annexin A1 in the promotion of tumor forming capacity in a model of human breast cancer." (PMID 33800279, 2021). "Others have also shown a better overall survival in patients with Annexin A1 positive primary breast cancers." (PMID 33800279, 2021). "The gene mapping of 24 DEGs through PubMed, OMIM, MeSH, and PMC databases provided eight significant breast cancer associated genes: ID4, NCOA1, RHEB, PDZK1, PLAUR, AKC1R2, ANXA1 and SLIPI." (PMID 33593445, 2021). "For instance, ANXA1 has been reported to be upregulated in breast cancer, hepatocellular carcinoma, and melanoma while downregulated in gastric cancer, prostate cancer, and oral cancer." (PMID 33959206, 2021). "For example, in breast cancer, ANXA1 tends to inhibit cancer cell proliferation and metastatic potential." (PMID 33959206, 2021). "On the contrary, ANXA1 has tumor promoter roles in pancreatic cancer, breast cancer, liver cancer, lung cancer, thyroid cancer and esophageal cancer." (PMID 34439260, 2021). "In the Human Protein Atlas, expression of Annexin A1 (p=0.025) and CEACAM1 (p=0.007) was associated with an increased survival in breast cancer patients." (PMID 34712237, 2021). "Previous studies reported that ANXA1 inhibition reduces tumor growth and immunogenicity activation in breast cancer." (PMID 34522794, 2021).
breast carcinoma (continued). "In an MMTV-PyMT driven allograft model of breast cancer, Annexin A1 depletion markedly delayed tumor formation in both immuno-competent and immuno-deficient mice and induced epithelial to mesenchymal transition and upregulation of basal markers." (PMID 33800279, 2021). "Cao and collaborators showed that, despite that breast cancers frequently display downregulation of AnxA1, this protein is upregulated in the triple-negative subtype." (PMID 34571894, 2021). "It has been shown that AnxA1 promotes the polarization of macrophages towards the M2 phenotype and induces the expression of IL-10 thus facilitating breast cancer progression and metastasis." (PMID 34208346, 2021). "Several of the LXRE genes predicted increased regression-free survival in breast cancer subjects, among which Ptgs2, Mfge8, Anxa1, Spp1, S100a9 and Cd14 are biomarkers for MDSC and Treg cells." (PMID 33780491, 2021). "ANXA1 can enhance the function of regulatory T cells (Tregs) and reduce the survival rate of patients with breast cancer." (PMID 33816497, 2021). "In a polyoma middle T antigen-driven allograft model of breast cancer, Annexin A1 depletion markedly delayed tumor formation, induced epithelial to mesenchymal transition and upregulated basal markers." (PMID 33800279, 2021). "FPR1 expression was also reported in breast cancer and it can be activated, in an autocrine manner, by the N-terminal peptide of AnxA1, which is secreted by the triple-negative breast cancer cell line, MDA-MB-231." (PMID 34571894, 2021). "Annexin A1 protein expression as measured by immunohistochemistry is consistently decreased in primary breast cancers relative to normal mammary gland or benign lesions, with expression most commonly retained in poorly differentiated TNBC or basal-like tumors." (PMID 33800279, 2021). "Here, we sought to clarify the role of Annexin A1 in TNBC growth and metastasis by comprehensive evaluation of clinical and experimental datasets and by manipulating endogenous Annexin A1 expression in xenograft and allograft models of breast cancer." (PMID 33800279, 2021). "Annexin A1 (AnxA1) functions as a suppressor of EMT and metastasis in breast cancer, and AnxA1 deficiency is associated with poor prognosis and metastasis." (PMID 34439323, 2021). "In breast cancer, it has been described that AnxA1 supports the metastatic process by promoting the TGF-β/Smad signaling and the subsequent EMT." (PMID 34208346, 2021). "Another study also showed that AnxA1 displays pro-angiogenic functions in breast cancer by supporting the activation of the nuclear factor-kappa B (NF-kB) transcriptional factor." (PMID 34571894, 2021). "For example, ANXA1 in peripheral blood mononuclear cells was found to be the diagnosis marker for solid tumors, such as breast cancer, lung cancer, and melanoma." (PMID 33066530, 2020). "In this study, we found that DCST1-AS1 binds to ANXA1 to promote TGF-β-induced epithelial–mesenchymal transition (EMT) processes in breast cancer cells." (PMID 32226772, 2020). "The overexpression of ANXA1 in highly aggressive breast cancers has led many researchers to focus on its role in invasion and metastasis." (PMID 32226772, 2020). "We analyzed TCGA database and found that ANXA1 is expressed in several breast cancer subtypes (luminal, HER2+, and TNBC), which have different morphological, clinical, and therapeutic responses." (PMID 32226772, 2020). "In conclusion, DCST1-AS1 promotes TGF-β-induced EMT and enhances chemoresistance in TNBC cells through ANXA1, and therefore represents a potentially promising target for metastatic breast cancer therapy." (PMID 32226772, 2020). "ANXA1 protein expression in breast cancer tissues was calculated by using anti-ANXA1 antibody staining." (PMID 31461932, 2019). "Increasing evidence indicates that Annexin A1 plays anti-inflammatory effects in Rheumatoid Arthritis35 and promotes breast cancer progression and metastasis." (PMID 31138830, 2019).
breast carcinoma (continued). "Further evidence that annexin A1 impacts oncogenic processes by altering miRNA synthesis was obtained by overexpressing this protein in breast cancer cells." (PMID 29462943, 2018). "This occurred indirectly through the stimulation of c-myc downstream of enhanced NFκB activity in breast cancer cells overexpressing annexin A1." (PMID 29462943, 2018). "Down-regulation of ANXA1 by 4-OH-TAM treatment points to the possibility that co-treatment of breast cancer cells with trastuzmab and TAM can enhance the sensitivity of breast cancer cells to trastuzmab." (PMID 29416786, 2018). "In breast cancer, ANXA1 is highly expressed and modulates activation of M2 macrophage, which in its turn promotes angiogenesis, tumor progression and adaptive immune response." (PMID 30157864, 2018). "To verify ANXA1 as a biomarker for basal vs. luminal subtypes, we performed RNA-seq to measure transcripts of three breast cancer cell lines: HCC1599 (basal), MB-157 (basal), and MCF-7 (luminal)." (PMID 29971090, 2018). "Our previous studies emphasized that ANXA1 modulates cell adhesion and migratory properties during breast cancer initiation and tumorigenesis." (PMID 29233185, 2017). "Here, we investigated the role of Annexin A1 (ANXA1), a well characterized immunomodulatory protein on macrophage polarization and the interaction between macrophages and breast cancer cells." (PMID 29263330, 2017). "Bioluminescence imaging confirmed that the ANXA1+/+ mice injected with 4T1 murine breast cancer cells exhibited increased luminescence compared with ANXA1−/− mice." (PMID 29263330, 2017). "Yet, both the studies emphasized a strong link between ANXA1 and migratory properties of breast cancer cells." (PMID 29233185, 2017). "AMPK activation was also predicted by upstream kinase analysis, and this negative correlation was consistent with previous reports wherein ANXA1 knockdown in breast cancer cells activated AMPK." (PMID 29233185, 2017). "With several reports suggesting correlation between ANXA1 and breast cancer outcome, we earlier focused on characterizing ANXA1-responsive changes in global proteome during breast cancer initiation and breast cancer tumorigenesis." (PMID 29233185, 2017). "Despite ANXA1 being considered a prognostic marker, its status in tumor progression and survival in breast cancer remain contradictory." (PMID 29233185, 2017). "We have previously reported that ANXA1 can increase NF-KB activity promoting breast cancer migration and metastasis and ANXA1 can regulate miR expression and function in breast cancer." (PMID 27105503, 2016). "Activation of NF-κB by ANXA1 was previously shown by us to result in the constitutive activation of NF-κB and subsequent effects on migration and metastasis of breast cancer cells." (PMID 27105503, 2016). "This study reports a novel regulatory circuit between ANXA1, NF-kB, c-myc and miR-196a which regulates breast cancer cell proliferation and tumor growth." (PMID 27105503, 2016). "Here, we show that miR196a was highly expressed in ER+ MCF-7 breast cancer cells when compared to normal mammary gland cells, with expression levels negatively correlating to ANXA1." (PMID 27105503, 2016). "In both TCGA patient samples and cell lines, annexin A1 levels were significantly higher in basal-like breast cancer than luminal and Her2/neu-positive breast cancer." (PMID 26000884, 2015). "These analyses allow us to explore the potential of ANXA1 as a marker for breast cancer outcome prediction and treatment response." (PMID 26137966, 2015). "We found TNBC cell lines expressing higher endogenous levels of annexin A1 to be associated with overactivation of EGFR, c-Met, and pAKT pathways compared to expression levels in ER+ breast cancer cell lines." (PMID 26000884, 2015). "The purpose of this study is to evaluate the association between ANXA1 expression, BRCA1/2 germline carriership, specific tumor subtypes and survival in breast cancer patients." (PMID 26137966, 2015).
breast carcinoma (continued). "Altogether, our findings stress the importance of ANXA1 for prognosis and possibly for therapy resistance in breast cancer." (PMID 26137966, 2015). "Our in-silico analysis of TCGA-breast cancer dataset demonstrated that annexin A1 mRNA expression is higher in basal subtype compared to luminal and HER2 subtypes." (PMID 26000884, 2015). "In this study, we sought to clarify the role of annexin A1 in the biology of breast cancer by examining its role in basal like subtype." (PMID 26000884, 2015). "Annexin A4 enhances NF-κB subunit p50 transcriptional activity, and Annexin A1 expression positively correlates with NF-κB activity in breast cancer metastasis." (PMID 25222280, 2014). "The present study provides evidence of the existence of a relationship between ANXA1, miRs and NF-κB and a unique miR signature in MCF7 breast cancer cells over-expressing ANXA1." (PMID 25536365, 2014). "MDA-MB-231 cells are triple-negative and highly aggressive breast cancer cells that express high levels of ANXA1." (PMID 25536365, 2014). "On the other hand, proliferation stimulation was observed in hepatocytes, in which AnxA1 was related to EGF, and in breast cancer; in the latter, it was associated with formyl peptide receptor (FPR2) binding and increased levels of cyclin D1." (PMID 24719523, 2014). "On the other hand, an elevated expression of ANXA1 has been demonstrated in hepatocellular cancer, pancreatic cancer, glial tumors, and even in breast cancer, reinforcing the contradictory findings to date." (PMID 24782913, 2014). "Recently, the prognostic value of Annexin A1 expression has been reported in lung cancer, head neck cancer, bladder cancer and breast cancer, most of which report Annexin A1 overexpression indicates a poorer prognosis." (PMID 23786757, 2013). "ANXA1 is down-regulated in breast cancer and has protective roles against the proliferative action of estrogens in cancer cells." (PMID 23791816, 2013). "Annexin A1 (ANXA1, fold change 7.1) has been shown to have oncogenic potential in breast cancer progression and metastasis and was significantly correlated with unfavorable prognostic features of breast cancer." (PMID 23148692, 2012). "Additionally, ANXA1 exhibits pro-angiogenic effects in breast cancer, notably through the activation of the nuclear factor-kappa B (NF-κB) signaling pathway." (PMID 41283264, 2025). "The AnxA1/FPR1 autocrine axis can promote invasiveness in breast cancer." (PMID 40538442, 2025). "Furthermore, ANXA1 has been shown to facilitate tumor invasion in breast cancer through NF-κB activation and MMP-9 expression." (PMID 40332093, 2025). "Furthermore, in the case of antitumoral action, ANXA1 is involved in the inhibition of cell proliferation, promotion of apoptosis, and reduction of cell motility, as shown in breast cancer (triple negative) and prostate cancer." (PMID 40227604, 2025). "Strong ANXA1 expression has been reported in various malignancies, such as melanoma, glioma, breast cancer, lung cancer, hepatocellular carcinoma, and CRC, including LARC, being mostly associated with a poor prognosis along with a reduced overall survival (OS) and disease-free survival (DFS)." (PMID 41283264, 2025). "ANXA1 expression is significantly higher in TNBC compared to other breast cancer subtypes." (PMID 40744683, 2025). "The downregulation of ANXA1 in breast cancer tissues under normal conditions may indicate the tumor's evasion of an effective immune response." (PMID 40744683, 2025). "ANXA1 expression varies in different types of breast cancer." (PMID 38892394, 2024). "Moreover, there are some subtypes of breast cancer where ANXA1 expression is reduced, with several studies reporting decreased ANXA1 expression in ductal carcinoma in situ and invasive ductal carcinoma compared to normal and benign tissues." (PMID 38200229, 2024).